CAP1 (cyclase associated actin cytoskeleton regulatory protein 1)
Diseases named in the same sentence as CAP1 in open-access papers (continued):
Sharing a sentence is not in itself a finding about the gene and the disease.
cancer (continued). "Although no remarkable up-regulation of CAP1 was detected in the four cancer cell lines tested in a panel, elevated S308/S310 phosphorylation on CAP1 was detected in cancer cells as compared to the control cells." (PMID 30894654, 2019). "If no up-regulation of CAP1 in human cancers, then de-regulated functions of the protein is likely to be important for its role in cancer cells." (PMID 30894654, 2019). "As a cytoskeletal protein, CAP1 was not originally expected to play a role in the proliferative transformation of cancer cells, and such a role had rarely been explored." (PMID 31151140, 2019). "Therefore, signaling through CAP1 is likely at least partially responsible for PDGF to stimulate actin cytoskeletal reorganization and cancer cell invasiveness." (PMID 30894654, 2019). "To test if Snail may mediate the regulation of E-cadherin by CAP1, we looked into Snail expression and found that CAP1 knockdown BT-549 and MDA-MB-231 cancer cells had significantly up-regulated Snail levels." (PMID 27173014, 2016). "Interestingly, cancer-linked mutations in both CAP1 and CAP2 are enriched in the N-terminal domain, with the hot spot mutations in CAP1 are located at the Arg-29 residue, which is not conserved between the two isoforms." (PMID 31718088, 2019). "We next looked into if the confluency of the culture may influence CAP1 expression, also including the non-metastatic cancer cell line MCF-7." (PMID 27173014, 2016). "While up-regulated CAP1 universally stimulates the invasiveness of human cancers may be a tempting model, the role for CAP1 in human cancers does not appear to be that simple and clear-cut." (PMID 27173014, 2016). "Finally, we demonstrate opposite roles for CAP1 in metastatic and non-metastatic cancer cells." (PMID 31151140, 2019). "Furthermore, we demonstrate that CAP1 regulates FAK and cell adhesion, but not ERK or cancer cell proliferation." (PMID 30894654, 2019).
tumor (25 papers, 2015 to 2026). "First, low tumor-specific CAP1 protein expression was associated with anthropometric measures indicating a higher adiposity status and with unfavorable tumor characteristics linked to tumor aggressiveness." (PMID 32560703, 2020). "Interestingly, S100A4, a protein recently found to be produced by LECs and to promote sprouting during tumor-associated lymphangiogenesis, emerged as one of the most strongly upregulated genes in the skin in both the cap1 and cap2 subsets and also in valve LECs." (PMID 41186588, 2026). "In this study, highly abundant Ezrin (EZR), Talin-1 (TLN1), Adenylyl cyclase-associated protein 1 (CAP1), and Moesin (MSN) have been used as exosomal tumor biomarkers." (PMID 39001524, 2024). "These modifications have also been associated with tumor progression together with PML ubiquitination and phosphorylation at S402 and S518, and CAP1 phosphorylation by GSK3B at T307, S308 and S31034–37." (PMID 35292711, 2022). "Recently, there have also been a number of studies suggesting that CFL1 and CAP1 work in conjunction to influence the aggressiveness of tumor development." (PMID 37226274, 2022). "PhosphoProtein analysis from Clinical Proteomic Tumor Analysis Consortium (CPTAC) showed that CAP1 protein expression was higher in male LUAD patients than female LUAD patients." (PMID 34636991, 2022). "Patients with low CAP1 tumor expression had worse long-term survival, both in terms of BCSS (LogRank Ptrend= 0.002) and OS (LogRank Ptrend < 0.001), compared to the patients with tumors of moderate to high CAP1 expression." (PMID 32560703, 2020). "A reduced BCSS and OS for patients with low tumor-specific CAP1 protein expression compared with intermediate and high expression was observed." (PMID 32560703, 2020). "First, this is the largest study of tumor-specific CAP1 expression of its kind allowing for patient stratification and multivariable analyses adjusted for relevant confounders." (PMID 32560703, 2020). "Univariable Cox analyses demonstrated that low CAP1 tumor expression was a prognostic indicator for inferior BCSS (HR = 0.46, 95% CI 0.28–0.77) as well as poor OS (HR = 0.54, 95% CI 0.38–0.78) among all patients." (PMID 32560703, 2020). "Patients with low CAP1 tumor expression tended to be more likely to received adjuvant endocrine treatment compared with patients with moderate to high CAP1 tumor expression (P = 0.002)." (PMID 32560703, 2020). "In contrast to earlier gene expression studies of CAP1, low CAP1 tumor expression at the protein level was more frequent among patients with histologic grade III, high Ki67, or ER-negative tumors, indicating more aggressive tumors phenotypes." (PMID 32560703, 2020). "In the present study, only a modest positive correlation between RETN and CAP1 tumor expression was found." (PMID 30524378, 2018). "We found that CAP1 protein expression gradually increased in 9 EOC tissues from 3 tumors classified as G1 to G3 (3 tissues from each tumor) in comparison with 1 normal ovarian tissue sample in which CAP1 expression was barely detected." (PMID 25652936, 2015). "High proportion of CAP1 positive tumor cells (> 30%) was prognostic of shorter OS." (PMID 32560703, 2020). "CAP1 was associated with poor tumor characteristics with higher CAP1 expression among estrogen receptor (ER)-negative tumors, relative to ER-positive tumors (P = 0.025), and higher histological grades (P = 0.016)." (PMID 30524378, 2018). "Furthermore, immunohistochemistry of the 119 paraffin-embedded tissue sections of EOC also revealed that CAP1 immunostaining was located in the cytoplasm and was upregulated in the poorly differentiated tumor cells compared to the well differentiated ones." (PMID 25652936, 2015). "In addition, CAP1 was highly expressed in the poorly differentiated tumor specimens compared to the well differentiated ones; similar results were obtained for Ki-67 expression." (PMID 25652936, 2015).
tumor (continued). "We divided the tumor specimens into 2 groups according to the expression of CAP1." (PMID 25652936, 2015). "The tumor size (T1–4) was positively correlated with the number of CFL1+CD326+ CTCs, and the type of epithelium was correlated with the number of CAP1+CD326+ CTCs." (PMID 37226274, 2022). "CAP1 remained a marker of poorer BCSS and OS after adjustments for age at diagnosis, tumor size, and any axillary lymph node involvement." (PMID 32560703, 2020). "Low CAP1 remained an indicator of poor BCSS also in multivariable models adjusted for age at diagnosis, tumor size, and lymph node involvement." (PMID 32560703, 2020). "Furthermore, according to these 7 key genes (ABCB1, CAP1, EGFR, ITGB1, MAPK1, PPARG, SNCA), we plotted the KM curves to show the survival state of high and low expression groups in tumor samples from the TCGA-PAAD dataset." (PMID 37857015, 2023). "Correlations between the number of CTCs and immune cells expressing CAP1 and PFN1 may reflect the peculiarities of the molecular mechanisms of the tumor-host relationship in the pathology." (PMID 37226274, 2022). "Another modified peptide, CAP1-6D, an epitope of CEA, has been modified to improve the binding to MHC-I complex and has been shown to trigger a more potent CTL response, and T cells activated have been shown to be cross-reactive with wild-type CAP1 and to recognize CEA+ HLA-A2+ tumor cells." (PMID 33080888, 2020). "Overall, patients with CAP1-low tumors had impaired BCSS (adjusted hazard ratio: HRadj = 0.52, 95% CI 0.31–0.88) and OS (HRadj = 0.64, 95% CI 0.44–0.92) compared with patients having high CAP1 tumor expression." (PMID 32560703, 2020). "In our tumor tissues, we observed the sporadic presence of two isoforms of CAP1 with a high increase versus the non-tumoral tissues (4.3× and 4.7×." (PMID 28686225, 2017). "Based on the analysis of the number of subpopulations expressing CFL1, PFN1 and CAP1, the characteristics of CTCs pools and peripheral blood leukocyte pools in patients with HNSCC were given in relation to the main clinical and pathological characteristics of the tumor." (PMID 37226274, 2022).
infection (19 papers, 2009 to 2025). The state of being infected such as from the introduction of a foreign agent such as serum, vaccine, antigenic substance or organism. "Further, in contrast to YFV-Asibi cap1, only few mosquitoes were positive for viral RNA in legs plus wings after oral feeding suggesting a role of the midgut barrier for the reduced infection rates observed for the cap0 variant." (PMID 39356716, 2024). "Further, an initial faster replication rate, as it was observed for YFV-Asibi cap1, seemed to allow the cap0 variants to replicate above the threshold in the later course of infection." (PMID 39356716, 2024). "It was recently demonstrated that an Adenylate cyclase associated protein, Cap1, localized as bright spots in the cytoplasm of the infection hyphae in M. oryzae." (PMID 23935502, 2013). "The dissemination of YFV-Asibi cap1 into secondary tissues continuously increased and reached dissemination rates of more than 80% from day ten post-infection onwards." (PMID 39356716, 2024). "Nevertheless, viral replication seemed to occur for both DENV cap1 and cap0 after intrathoracic infection, with cap1 growing to higher titers than cap0." (PMID 39356716, 2024). "In Aag2 cells, YFV-Asibi cap0 produced an over 1 log lower viral titer than the cap1 virus on day three post-infection." (PMID 39356716, 2024). "The infection experiments in mosquito cells revealed that in C6/36 cells an efficient growth was observed for YFV-Asibi cap1, peaking already three days post-infection (3.8 x 106 PFU/ml)." (PMID 39356716, 2024). "Specifically, while (+)-sense RNAs generated in vitro by reovirus cores had cap1, ~40% of (+)-sense RNAs synthesized during the infection of L929 cells at 5–11 h post infection (hpi) had cap2 structures." (PMID 33668598, 2021). "Their findings suggested a switch from m7G(5′)ppp(5′)GmpCp (cap1) to pGp 5′-termini as infection progressed, with only 2% of ribosomal reovirus mRNAs containing cap1 at the 10–13 hpi time point." (PMID 33668598, 2021). "TRP47 interacts with CAP1 (actin binding protein adenylate cyclase protein 1) at the morula membrane interface and changes the distribution of CAP1 during infection." (PMID 27303657, 2016). "Cap1, Gpx3 and Ybp1 are also vital for C. albicans virulence in a Galleria mellonella model of infection, and Cap1 is important for virulence in a Caenorhabditis elegans infection model in nematode hosts that have a functional NADPH oxidase." (PMID 25723552, 2015). "The observation that Cap1 is dispensable for virulence in murine systemic models of infection was unexpected, as certain genes that are induced by Cap1 in response to H2O2, such as CTA1 and TRX1, are important for C. albicans survival in such models." (PMID 25723552, 2015). "We performed a detailed analysis of Ct260, CdsQ, Cap1 and Ct618 localization at 12 and 24 h post infection by immunofluorescence microscopy." (PMID 19750218, 2009). "While YFV-17D cap1 reached a titer of 667 PFU/ml at five days post-infection in CCL-125 cells, the cap0 variant did not exceed the detection limit." (PMID 39356716, 2024). "The expression of CAP1 was severely down-regulated by the SFVmfu infection in TE671 cells." (PMID 31969530, 2020). "Consequently, all infected vines expressing CAP-1 were in good health in spite of the infection and showed a high frequency of spring bud break." (PMID 30787937, 2019). "Loss of Cap1 or its regulators Gpx3 and Ybp1 attenuates virulence in some, but not all infection models." (PMID 25723552, 2015). "In response to infection, in male mice, the TACC2, BUB1B, ATP5MC3, and MYO1E, and in female mice, the CAP1, MRPL2, COX5A, KLHL21, PDIA6, TSPO, and USP14 had direct interaction with TP-53." (PMID 35844510, 2022). "Mice vaccinated with rTm-WAP-F8+Na-GST-1, rTm-CAP-1, Tm-ES, or Montanide ISA 720 adjuvant alone were challenged orally with 300 embryonated T. muris eggs and evaluated 15 days post-infection for intestinal worm burden by direct microscopy." (PMID 30153307, 2018).
infection (continued). "Whether mosquitoes possess a receptor or protein able to discriminate between cap1 and cap0 similar to RIG-I or IFIT1 in vertebrates and whether it is constitutively expressed or upregulated upon infection like ISGs in vertebrates remains to be investigated." (PMID 39356716, 2024). "The other infectious pools, AAP2, AAP3, BAP1, BAP2, BAP3, CAP1, and CAP2 might have carried the single infection of D. immitis, whose reactions putatively yielded 477-bp amplicons." (PMID 34027007, 2021). "In addition, among 46 TRP32 target genes previously found to be differentially expressed during infection, 8 are also TRP47 targets, including CAP1, CMC1, HLX, ING1, MTFR2, NAT10, PARP16, and POLDIP3." (PMID 30408047, 2018). "Consequently, since the authors did not assess viral load shortly after oral feeding, it is difficult to really compare the infection rates between DENV cap1 and cap0 in mosquitoes, also because fewer cap0 infected mosquitoes than cap1 infected mosquitoes were examined." (PMID 39356716, 2024). "Furthermore, no LNPs-Cap1-mRNA-Luc were observed to spread to the liver and kidneys, and the LNPs remained localized to the injection site at 12 h after infection." (PMID 38543744, 2024).
kidney disease (2 papers, 2017 to 2020). "Given this evidence and the fact that CAP1 has not been studied in the context of kidney disease, it appears to be an excellent candidate molecule for further investigation." (PMID 28831120, 2017).
metabolic disorders (1 paper, 2015). "This suggests that resistin may act through TLR-4 and not CAP1 during Nb infection, and the importance of CAP1 in resistin-mediated effects may be more significant in metabolic disorders." (PMID 25568944, 2015).
CAP1 also shares sentences with these, for which no sentence is quoted: lymph node metastasis (4 papers); colorectal cancer (3); bone metastasis (2); cardiovascular diseases (2); colon cancer (2); lymphoma (2); pancreatic ductal adenocarcinoma (2); amyloidosis diseases (1); brain cancer (1); cervical squamous cell carcinoma (1); chronic obstructive pulmonary disease (1); cognitive decline (1); diabetes (1); heart diseases (1); Hepatic steatosis (1); ichthyosis (1); Infertility (1); lung squamous cell carcinoma (1); lymphopenia (1); metastatic colorectal cancer (1); metastatic disease (1); nephrotic syndrome (1); osteoporosis (1); rheumatoid arthritis (1); severe acute respiratory syndrome (1).